MMP9 (matrix metallopeptidase 9)
Diseases named in the same sentence as MMP9 in open-access papers (continued):
Sharing a sentence is not in itself a finding about the gene and the disease.
tumor (continued). "As we all know, β-catenin involves in the regulation of CyclinD1 and MMP9 in tumor cells." (PMID 32760218, 2020). "Among MMPs, MMP2 and MMP9 have pivotal role in angiogenesis, tumor proliferation, and invasion." (PMID 31929760, 2020). "CCL2 also promotes the recruitment of tumor-associated macrophages (TAMs) that may secrete VEGF and the proteolytic enzyme MMP-9, which is involved in the vascularization of tumor tissues." (PMID 32019112, 2020). "Neutrophil-derived MMP9 is more likely to activate and participate in pre-tumor functions." (PMID 33363026, 2020). "MMP9 is a key metalloproteinase for extracellular matrix (ECM) degradation during tumor invasion." (PMID 32090682, 2020). "We have previously shown that RUNX2, CD44s, and MMP9 are highly expressed in tumor tissue." (PMID 33062960, 2020). "Likewise, preventing mesenchymal transition by silencing ZEB1 or by pharmacological inhibition of the MMP9/PAR1 axis significantly reduced the ability of tumor cells to survive the anti-tumor activities of macrophages." (PMID 32809114, 2020). "miR-483-3p could inhibit the cell growth, migration and invasion of tumor cells by directly targeting matrix metalloproteinase 9 (MMP9)." (PMID 33659208, 2020). "Furthermore, MAPK1 is responsible for mediating the expression of the matrix metallopeptidase 9 (MMP-9), a molecule that has been associated with tumor migration." (PMID 32211411, 2020). "Additionally, MMP-9 expression in migratory and invasive tumor cells is thought to be regulated by transcription factors NF-κB, AP-1, and Sp-1, which are located in its promoter region." (PMID 32708058, 2020). "The MMP9 levels were inhibited with GA and CA about 60% in tumor cells at both doses, while in ascites fluid GA inhibited MMP9 by 38.93% and 66.87% at dose of 40 or 80 mg/kg, while treatment with CA inhibited MMP9 by 53.28% and 73.94% at some doses compared to the saline-treated control group." (PMID 33261130, 2020). "Among a variety of stimuli, TPA, as a tumor promoter, has been reported to induce MMP-9 expression by upregulating transcription factors, such as activator protein-1 (AP-1), signal transducer and activator of transcription-3 (STAT3), and nuclear factor kappa B (NF-κB)." (PMID 31893611, 2020). "MMP-9, MMP-2, uPA, and VEGF, as metastasis and angiogenesis-associated proteins, promote extracellular matrix degradation and new blood vessel development, leading to enhanced tumor invasion and growth." (PMID 32429376, 2020). "Most studies reported that TAGL acts as a tumor suppressor, inhibiting cell migration, suppressing the 92-kDa type IV collagenase (MMP-9), and being down-regulated by the Ras pathway as well as silenced through epigenetic mechanisms, which involve TAGL promoter hypermethylation." (PMID 32353950, 2020). "These proteins appear to participate in a signaling pathway that leads to tumor initiation and progression through the action of MMP-9 (matrix metallopeptidase 9), which degrades basement membranes and the extracellular matrix, facilitating the spread of tumor cells." (PMID 33053887, 2020). "Additionally, MMP-2 and MMP-9 released by MCs are capable of facilitating the tumor vascularization and promoting tumor invasiveness, respectively." (PMID 31256327, 2020). "Additionally, the protein expressions of MMP-2 and MMP-9, two proteolytic enzymes of matrix metalloproteinases (MMPs) frequently playing a critical role for tumor invasion and distal metastasis, exhibited an identical pattern of Jagged2 among the three groups." (PMID 32792862, 2020). "In many studies, inhibition of MMP-2 and MMP-9 decreased tumor angiogenesis." (PMID 32351671, 2020). "Metalloproteinase 9 (MMP9) and Resistin‐like molecule β (RELMβ) were the only two proteins that were specifically identified as being differentially secreted in the T‐cell co‐culture assay when tumor‐derived neutrophils were present." (PMID 31793740, 2020).
tumor (continued). "Moreover, the miR-31-5p mimics and si-PEX5 decreased the levels of MMP2 and MMP9, key molecules mediating tumor cell invasion." (PMID 32373215, 2020). "Moreover, deletion of c-Myc in macrophages resulted in the reduced expression of pro-tumor genes (e.g., VEGF, MMP9, and HIF1a) in TAMs and reduced tumor development in a mouse model of melanoma." (PMID 32486098, 2020). "It is generally accepted that MMP-2 and MMP-9 are involved in tumor metastasis." (PMID 32978501, 2020). "Moreover, increased expression levels of MMP2 and MMP9 helped to enhance tumor cell invasion ability." (PMID 32269963, 2020). "MMP-2 (gelatinase-A) and MMP-9 (gelatinase-B) are the markers of tumor invasion." (PMID 33233701, 2020). "Then we confirmed whether matrine can also affect CXCR4, MMP-2, and MMP-9 mRNA levels in tumor cells." (PMID 32630806, 2020). "We subsequently conducted a mechanistic study to explore the role of IGF signaling in the expression of MMP-9 in Plasmodium-infected tumor-bearing mice and found a significant reduction in the p-AKT and phosphorylated p42/44 MAPK levels in the infected group compared with the uninfected group." (PMID 32972437, 2020). "Additionally, a cooperative effect of MMP-2 and MMP-9 was demonstrated in an in vivo experimental model establishing the angiogenic phenotype and invasiveness of tumor keratinocytes." (PMID 31921634, 2019). "Furthermore, consistent with the in vitro data, we confirmed that phosphorylation of p38MAPK was suppressed by α-H treatment in tumor tissues and reported the downregulation of MMP-9 and a significant increase in TIMP-1 expression." (PMID 31551765, 2019). "MMP activity analysis showed that along with a significant plasmatic expression and activation, a tissular MMP-9 expression (active and inactive MMP) was detectable in the epithelial and the stromal areas of the invasive tissues (MMP-9 tumor/stroma, r = 0.89, p=0.001, Pearson)." (PMID 31885577, 2019). "Moreover, results of immunohistochemical analysis demonstrated that SNHG7 promoted cell proliferation in tumour tissues (Ki‐67), as well as increased expression of metastasis related protein (MMP‐9)." (PMID 31478234, 2019). "Non-remissive and later stage BrCa was reported to be correlated with CCL5 expression, possibly due to its ability to promote pro-invasive factor MMP9 and monocyte migration to the BrCa tumor site, in which they undergo polarization allowing them to support tumor progression through angiogenesis." (PMID 30850664, 2019). "MMP2 and MMP9 are closely involved in tumor invasion and migration in many malignant tumors." (PMID 31263453, 2019). "MMP-2 and MMP-9 expression in the tumor was further detected by a western blot assay (d e)." (PMID 31637006, 2019). "MDSCs from MMP9-knockout mice have a significant reduction in their tumor promoting activity." (PMID 31057536, 2019). "MMP2 and MMP9 are important protein pathways for tumor invasion and metastasis." (PMID 31110076, 2019). "Finally, we measured in prostate tissue obtained from WT, CLUKO, TRAMP, and TRAMP/CLUKO, the expression and activity of ECM metalloproteinases (MMP-2 and MMP-9) that are known to be involved in tumor dissemination being regulated by the NF-κB pathway." (PMID 31885575, 2019). "Importantly, the induction of VEGF and MMP9 expression by macrophages from the tumor microenvironment is also one of the important sources." (PMID 31824776, 2019). "MMP-9 was shown to act as a controller of the tumor neovascularization." (PMID 31143300, 2019). "Moreover, MMP-2 and MMP-9 are crucial for angiogenesis and are possibly correlated with tumor growth." (PMID 30621167, 2019). "We report that the acquisition of tumor aggressiveness in patients is dependent on close associations prevailing between NOS2 and IL-10 synthesis and between IL-17A, TGF-β, and MMP-9 and identifies IL-17A as a possible key predictor of LSCC aggressiveness and resistance to therapy." (PMID 31885577, 2019).
tumor (continued). "In addition, high levels of MMP-9 have been detected at the invasive tumor front (ITF), thus many studies describe MMP-9 as a potential marker of invasive OSCC." (PMID 30927923, 2019). "In conclusion, SCLC CTCs express MMP-9 and a range of cathepsins for proteolysis and, aside from tissue degradation, these enzymes are involved in cell signaling, survival, and the chemoresistance of tumor cells." (PMID 30669448, 2019). "Thus, we investigated the effect of Tregs on the expression of MMP9, which induces angiogenesis, tumor growth, and metastasis." (PMID 31690033, 2019). "MMP2 and MMP9 are known to play a role in angiogenesis, tumor growth and metastasis." (PMID 30871117, 2019). "MMP-2 and MMP-9 participate in both early and late processes of tumor progression." (PMID 31839881, 2019). "Among the MMP members, the MMP-9 has been extensively studied in human cancers and has been shown to be closely related to the invasive potential and metastasis of different types of tumor cells." (PMID 31293204, 2019). "A potential explanation of this result could be an indirect effect of MesobsFab on the MSLN-driven secretion of matrix metalloproteases, notably MMP-7 and MMP-9 which have been described as promoting tumor invasion." (PMID 31354732, 2019). "Recent studies have shown that MMP9 increases tumor resistance to anti-PD-1." (PMID 31367490, 2019). "Several researchers have focused on the role of MMP-9 in tumor invasion and metastasis." (PMID 31037923, 2019). "In addition, MMP-9 expression was upregulated in tumor tissues compared with that noted in the paired adjacent non-tumor tissues in both CRC fresh tissues and a TMA cohort." (PMID 31293204, 2019). "We next determined if blocking MMP9 had direct effects on the tumor cells in vitro." (PMID 31727800, 2019). "Decreased tumour angiogenesis as observed by reduced tumour microvessel density in peritoneal dissemination xenografts after anti‐MMP9 antibody therapy may be unrelated to the increase in VEGF expression." (PMID 30941918, 2019). "In addition, the E-cadherin protein level was increased, whereas the MMP9, Twist, and Vimentin protein levels were decreased in the UA-treated xenograft tumor tissues as compared with those in the control tumor tissues." (PMID 31547587, 2019). "Additionally, linarin, a major active component of YFTL, inhibited tumor growth and metastasis via down-regulation of Akt and repressed the MMP-9-dependent invasion pathway." (PMID 30781674, 2019). "When the LOX inhibition group was compared with the control group, the enzyme activity of the active form of MMP-2 (62 kDa) in mouse tumor tissues was significantly decreased (P < 0.05) and the enzyme activity of the active form of MMP-9 (92 kDa) was significantly decreased (P < 0.05)." (PMID 31777578, 2019). "For instance, TAM-derived MMP-9 induces angiogenesis and tumor growth in melanoma." (PMID 31629410, 2019). "Either Sal-B or cisplatin also significantly decreased tumor tissue levels of MMP-9." (PMID 31726654, 2019). "MMPs, especially MMP-2 and MMP-9, play crucial roles in tumor invasion and metastasis." (PMID 30915362, 2019). "AURKA overexpression could also increase the expression of MMP-2, MMP-7, MMP-9, leading to tumor metastasis by degrading extracellular matrix proteins." (PMID 31706255, 2019). "When DANCR regulation was activated, MMP9 was upregulated, leading to tumor progression." (PMID 31798638, 2019). "The mRNA levels of Ccr7, Mmp9, c-Fos (Fos proto-oncogene, AP-1 transcription factor subunit), c-Jun (Jun), Ccl19 (C-C motif Chemokine Ligand 19) and Ccl21 were significantly reduced in tumor of CRE treated mice." (PMID 30781353, 2019). "The present study was undertaken to determine the target engagement of a novel, highly specific anti‐MMP9 antibody within the PDAC tumour microenvironment, and to define its therapeutic efficacy in combination with nab‐paclitaxel‐based cytotoxic chemotherapy in pre‐clinical PDAC models." (PMID 30941918, 2019).
tumor (continued). "To predict tumor invasiveness, we detected the expression of MMP9 in corresponding tumor sections." (PMID 31754093, 2019). "MMP-9 plays a vital part in the progression of tumor and angiogenesis." (PMID 30925799, 2019). "The suppressive effect of CA on MMP-2 and MMP-9 is associated with blockade of the activation of NFkB, as reported in liver cancer cells stimulated by PMA (activating protein 1), leading to a decrease in tumor growth and invasiveness." (PMID 31293975, 2019). "More than the degradation of extracellular proteins, some MMPs regulate tumor invasion through other mechanisms, for example, MMP-2 as well as MMP-9 could activate TGF-β to promote tumor invasion." (PMID 31406154, 2019). "Additionally, these neutrophils were shown to secrete increased amounts of MMP8 and MMP9, which facilitated tumor cell extravasation and metastasis." (PMID 31514474, 2019). "Assessment of MMP-2 and MMP-9 expression in the invasive tumor front may be helpful in the differentiation of verrucous carcinoma and squamous cell carcinoma of the oral cavity." (PMID 31344926, 2019). "Formononetin also demonstrates an inhibitory effect on the expression of matrix metalloproteinases (MMPs) such as MMP-2 and MMP-9 proteins, which play an essential role in the metastatic process of tumor cells as well as the regulation of angiogenesis in the maintenance of tumor cell survivability." (PMID 31402861, 2019). "In a word, our studies showed that BMAL1 could promote the tumor metastasis by increasing the expression of MMP9 at mRNA and protein levels." (PMID 31346317, 2019). "In xenograft models, we confirmed that knockdown of SKA1 could led to decreased N-cadherin and MMP9 and increased E-cadherin in xenograft tumor tissue." (PMID 31827398, 2019). "MMP-9 is one of the most important MMPs involved in tumor invasion and metastasis, whereas MMP-1 has also been reported to activate endothelial PAR-1 to facilitate endothelial permeability and transendothelial migration of tumor cells, and thus to promote metastatic dissemination." (PMID 30483898, 2019). "In addition, chronic stress increased the expression of VEGF, MMP-2, MMP-7 and MMP-9 in transplanted tumour tissue, and catecholamine hormones enhanced the expression of metastasis-related proteins." (PMID 31624248, 2019). "A significant increase in the odds ratio for survival occurred in the case of increased expression of MMP-9 investigated in the tumor and MMP-2 and TIMP-1 in the stroma; however, the chance of the patient’s survival increased most clearly in relation to TIMP-1P [OR=1.724]." (PMID 31223594, 2019). "Besides, tumor angiogenesis is regulated by MMP-9 expression through modulating the bioavailability of VEGF." (PMID 31387647, 2019). "Also, MMP9 and Snail/Slug were detected in the tumor tissue, suggesting the metastatic potential of the tumor." (PMID 31450740, 2019). "Overall, these data demonstrate that blocking MMP9 using SDS3 affected not only multiple intrinsic properties of tumor cells but also affected recruitment and activation of CD8+ T cells in the lung microenvironment, which ultimately contributed to an anti-metastatic immune response." (PMID 31727800, 2019). "However, data from this current study suggest possible roles for MMP-9 and N-Cad expression in that changes in the expression of these proteins correlated to changes in cell and tumor growth." (PMID 31391540, 2019). "Importantly, tumor-associated macrophages (TAMs) secrete membrane-bound or soluble proteases, such as MMP-2, MMP-9, and MMP-12, which are involved in ECM degradation and promote the infiltration of tumor-associated blood vessels." (PMID 31921634, 2019). "This study noted a difference between the serum and tumor tissue overexpression of MMP9." (PMID 31191742, 2019). "MMP-9 is believed to be involved in the development of diverse tumor types." (PMID 33817161, 2019). "MMP2 and MMP9 at the final step break and open the extracellular matrix to promote tumor invasion." (PMID 31225500, 2019).
tumor (continued). "Immunofluorescence analyses validated the expression of mesenchymal markers, N-cadherin, MMP-2 and MMP-9 were suppressed in mice tumor tissues; whereas the expression of epithelial marker, E-cadherin was increased in mice tumor tissues after treatment of mice with WZ35." (PMID 31703744, 2019). "A similar significant correlation was noticed in the case of MMP-9 in the tumor (P=0.0403)." (PMID 31223594, 2019). "Furthermore, MMP9 overexpression in correlation with MSLN overexpression showed increased tumor invasion and decreased survival in MM patients." (PMID 31191742, 2019). "In particular, the repression of Mmp9 expression might reduce the migratory capacity of tumor cells due to their inability to modify the ECM." (PMID 30857197, 2019). "In conclusion, these results indicate that ANE components (BQ chewing) may enhance tumor invasion and metastasis via stimulation of MMP-9 mRNA expression and secretion." (PMID 31831717, 2019). "Thus, E-cadherin, N-cadherin, vimentin, MMP2 and MMP9 were identified as attractive cancer targets that all play important roles in the context of tumour metastasis." (PMID 31423109, 2019). "RT-qPCR assays revealed that the expression of maspin affected the gene expressions of cyclin D1, p21, vimentin MMP2, and MMP9 in xenograft tumors, which suggested that maspin may modulate these genes to regulate tumor growth in vivo." (PMID 31861435, 2019). "The increased lactate secretion by tumor cells could result in an acidic peri-tumor microenvironment which induces MMP-9 expression and the release of other proteolytic enzymes to degrade components of the ECM." (PMID 31181802, 2019). "Also, MMP9 is involved in the degradation process of the tumor extracellular matrix and is a mediating factor for local invasion and distant metastasis of tumor." (PMID 31346317, 2019). "In addition, it regulated the expression of nuclear factor kappaB (NF-kB) and MMP9 at both protein and mRNA levels in tumor cells and SW780." (PMID 31508793, 2019). "It is proposed that propranolol inhibits vasodilation via beta-receptors, which decreases blood flow to the lesion; blocks the release of proangiogenic factors (e.g., VEGF, bFGF, MMP-2, and MMP-9), thus limiting the growth of IH; and induces apoptosis in endothelial cells, favoring tumor remission." (PMID 31700578, 2019). "However, TAMs were also found to directly contribute to tumor niche formation and tumor ECM shaping by producing proteolytic enzymes (MMP-2 and MMP-9) and matrix-associated proteins." (PMID 31591367, 2019). "However, in the analysis of 5-year survival, MMP-2 and MMP-9 both in tumor and stroma, as well as TIMP-1 in stroma, can be useful." (PMID 31223594, 2019). "Large amounts of strongly brown‐stained MMP‐9 signals were detected in the malignant tissues, mostly surrousssssnding the carcinoma cells, whereas markedly less and weak positive signals in the sections of benign tumours." (PMID 31264317, 2019). "Furthermore, it was shown that THBS1 up‐regulates MMP9 expression in endothelial cells and promotes tumor cell invasion." (PMID 31580518, 2019). "However, in contrast to the peritoneal dissemination tumour model, the efficacy of anti‐MMP9 antibody in the subcutaneous was reduced." (PMID 30941918, 2019). "The correlation between HMGA1 and MMP9 expression in late stage EEC samples raises the hypothesis that the upregulation of HMGA1 may trigger tumor invasiveness through MMP9 upregulation and consequently lead to patients’ poorer prognosis." (PMID 31096664, 2019). "Interestingly, primary tumor burden was unaffected, suggesting that inhibiting active MMP9 is primarily effective during the early metastatic cascade." (PMID 31727800, 2019). "Tumor invasion-related protein MMP-9 was significantly inhibited by fluoxetine." (PMID 30754643, 2019).